ARSG (arylsulfatase G)
Description:
Displays arylsulfatase activity at acidic pH towards artificial substrates, such as p-nitrocatechol sulfate and also, but with a lower activity towards p-nitrophenyl sulfate and 4-methylumbelliferyl sulfate. Catalyzes the hydrolysis of the 3-sulfate groups of the N-sulfo-D-glucosamine 3-O-sulfate units of heparin.
Synonyms: KIAA1001; USH4
Tractability: Antibody: UniProt predicts a signal peptide or a membrane-spanning region. PROTAC: ubiquitination databases record sites on it.
Target class: Enzyme; Hydrolase
Gene: Protein-coding gene on chromosome 17 (68,259,182 to 68,422,731, forward strand). Ensembl gene ENSG00000141337.
Subcellular location: Lysosome
Pathways (Reactome):
Metabolism: Glycosphingolipid catabolism
Metabolism of proteins: The activation of arylsulfatases
Gene Ontology:
Molecular function: arylsulfatase activity; N-sulfoglucosamine-3-sulfatase activity
Biological process: sulfur compound metabolic process
Cellular component: endoplasmic reticulum; extracellular region; lysosome; endoplasmic reticulum lumen
Genetic constraint (gnomAD): Loss-of-function variants: 34 observed, 45.45 expected, observed/expected ratio (o/e) 0.75, 90% interval 0.57 to 1. The upper end of that interval is the gene's LOEUF score, 1, which puts it in group 4 of 6, group 1 being the genes least tolerant of losing a copy. Missense variants: 572 observed, 658.06 expected, observed/expected ratio (o/e) 0.87, 90% interval 0.81 to 0.93. Synonymous variants: 215 observed, 252.19 expected, observed/expected ratio (o/e) 0.85, 90% interval 0.76 to 0.95.
Homologues: Orthologues: chimpanzee ARSG (99% identical), macaque ARSG (95% identical), dog ARSG (86% identical), rabbit ARSG (84% identical), rat Arsg (84% identical), guinea pig ARSG (83% identical), pig ARSG (83% identical), mouse Arsg (82% identical), tropical clawed frog arsg (62% identical), zebrafish arsg (54% identical), Drosophila melanogaster CG32191 (23% identical), Drosophila melanogaster CG7402 (22% identical), and 3 more. Paralogues in human: ARSA (35% identical), ARSD (34% identical), GALNS (34% identical), ARSF (33% identical), ARSH (31% identical), ARSL (31% identical), STS (31% identical), ARSI (24% identical), ARSB (23% identical), ARSJ (23% identical), SGSH (22% identical), SULF2 (20% identical), and 4 more.
Diseases named in the same sentence as ARSG in open-access papers:
ARSG is named in the same sentence as 25 diseases in open-access papers, as found by Europe PMC text mining. Sharing a sentence is not in itself a finding about the gene and the disease. The quoted sentences say what the papers report.
Usher syndrome (5 papers, 2020 to 2025). A syndromic diseae characterized by the association of sensorineural deafness (usually congenital) with retinitis pigmentosa and progressive vision loss. "In the past, biallelic variants in ARSG were tentatively assigned to cause “USH type IV” or atypical Usher syndrome." (PMID 39199020, 2025). "The third gene from our list associated with deafness is ARSG, involved in late-onset atypical Usher syndrome, with hearing and vision deficits appearing around the age of 40." (PMID 31927188, 2020). "PDZD7 may act as a modifier gene for USH, but HARS, ABHD12, CIB2, CEP250, CEP78, ESPN, and ARSG could be grouped in a separate syndromic “deaf–blindness” category, to avoid diagnostic pitfalls and misinformation during genetic counseling for Usher syndrome." (PMID 35353227, 2022).
Dystonia (3 papers, 2016 to 2025). An abnormally increased muscular tone that causes fixed abnormal postures. "A study in a Dutch patient group with musician's dystonia and writer's cramp found an accumulation of rare single nucleotide variants in the coding region of ARSG, which indicated that ARSG may function in the task-induced focal dystonia." (PMID 35273550, 2021). "Although many dystonias with a known genetic basis are generalized, there may be gene variants associated with task-specific dystonias, such as in arylsulfatase G in musician’s dystonia and writer’s cramp, with less association present in blepharospasm in one study." (PMID 40137895, 2025). "The fact that dogs carrying homozygous mutations or dogs deficient for ARSG develop ceroid lipofuscinosis and accumulate heparin sulfate in visceral organs and central nervous system leading to behavioral deficits made ARSG an attractive disease gene for musician’s dystonia." (PMID 28138320, 2016). "Some genome-wide association studies (GWASs) and replication studies have revealed correlations between single nucleotide polymorphisms (SNPs) of the ARSG, BDNF, NALCN, OR4X2, KIAA1715, and OR4B1 genes and dystonia." (PMID 35273550, 2021).
Usher syndrome, type 4 (3 papers, 2021 to 2025). "Recently several clinical reports of patients with ARSG mutations in have been proposed as Usher syndrome type 4 (USH4)." (PMID 40620763, 2025). "Another subtype, putatively referred to as MPS IIIE, is thought to result from arylsulfatase G (ARSG) dysfunction, but this has only been observed in animal models and has yet to be described in a human patient (most ARSG mutations are instead associated with Usher syndrome type 4 [OMIM 6181440])." (PMID 34073041, 2021).
breast carcinoma (1 paper, 2024). "ATG2A exhibits mutations in breast cancer, FRMD8 plays a tumor-suppressive role in breast cancer progression, ARSG is negatively correlated with positive prognosis, and differentially expressed genes upregulated by SAC3D1 are involved in regulating the cell cycle pathways in breast cancer cells." (PMID 39720180, 2024).
Cerebellar atrophy (1 paper, 2025). Cerebellar atrophy is defined as a cerebellum with initially normal structures, in a posterior fossa with normal size, which displays enlarged fissures (interfolial spaces) in comparison to the foliae secondary to loss of tissue. "ARSG-deficient ASTs and mice exhibit cerebellar atrophy, loss of Purkinje cells, and accumulation of autofluorescent and periodic acid–Schiff-positive storage material in Purkinje cells and other cells in the brain." (PMID 41295716, 2025). "American Staffordshire Terriers (ASTs) with a c.296G>A variant in ARSG develop progressive ataxia, cerebellar atrophy, and neuronal accumulation of autofluorescent storage material." (PMID 41295716, 2025). "In contrast to ASTs and mice with ARSG mutations, human patients generally do not exhibit neurological involvement, with the exception of two patients reported to have mild cerebellar atrophy without ataxia." (PMID 41295716, 2025).
Hearing impairment (1 paper, 2025). A decreased magnitude of the sensory perception of sound. "The owners of the affected dogs did not report signs of hearing impairment in their animals that occur in human subjects with ARSG mutations, but objective assessment of hearing was not performed." (PMID 41295716, 2025).
hypothyroidism (1 paper, 2022). Abnormally low levels of thyroid hormone. "Identification of larger numbers of USH type IV cases may answer the question on whether hypothyroidism is associated with ARSG defects." (PMID 35226187, 2022).
lysosomal storage disorders (1 paper, 2025). "One unique aspect of USH IV is the absence of neurological symptoms typically associated with lysosomal storage disorders, despite ARSG’s role in lysosomal metabolism." (PMID 40149483, 2025).
neuronal ceroid lipofuscinosis (1 paper, 2022). "A homozygous missense loss of function ARSG variant in a canine animal model resulted in sulfatase deficiency and neuronal ceroid lipofuscinosis, however, without affecting the retina." (PMID 35226187, 2022).
progressive ataxia (1 paper, 2025). "Like mice lacking a functional copy of this gene, American Staffordshire Terriers (ASTs) with an arylsulfatase G gene mutation suffer from progressive ataxia, but affected dogs have not been evaluated for the type of visual impairment that affects human patients and mice." (PMID 41295716, 2025).
progressive myoclonus epilepsy (1 paper, 2012). A rare group of disorders characterized by the development of myoclonic and tonic-clonic epileptic seizures associated with progressive degeneration of the nervous system. "Most of these known canine progressive myoclonus epilepsy (PME) genes are orthologues of the corresponding human syndromes and two new NCL candidate genes, ARSG and ATP13A2, have been identified for human NCLs." (PMID 22457775, 2012).
retinal degeneration (1 paper, 2025). Degeneration of the retina. "Because visual impairment and retinal degeneration are associated with ARSG variants in mice and human subjects, a study was undertaken to determine whether retinal function was also affected in dogs homozygous for the ARSG disease variant." (PMID 41295716, 2025).
retinal diseases (1 paper, 2025). "Finally, testing of ARSG should be considered for the genetic work‐up of apparent isolated inherited retinal diseases." (PMID 39199020, 2025).
sarcoma (1 paper, 2017). A usually aggressive malignant neoplasm of the soft tissue or bone. "Moreover, the detection by RT-PCR of specific sarcoma genes like ARSG,MYLK, and NBEA confirmed our assumption, even though the level of expression of ARSGand MYLK were lower than that of mouse sarcoma WEHI-164 cell line used as positivecontrol." (PMID 28430664, 2017).
tumor (3 papers, 2022 to 2025). "CASKIN2, TLE2, USP20, SPRN, ARSG, MIR106B, and MIR98 were considered to be substantially expressed in the low-risk group, suggesting that these genes may be PAAD tumor suppressor genes." (PMID 35077391, 2022). "For example, ARSG, CTH, PDK1, and PDK4 are heavily involved in cellular metabolism and oxidative stress regulation, pathways tightly coupled with tumor proliferation and survival under adverse microenvironmental conditions." (PMID 41153607, 2025).
ARSG also shares sentences with these, for which no sentence is quoted: deafness (3 papers); Atrophy (1); Blindness (1); focal dystonia (1); Hypertension (1); mucopolysaccharidosis (1); neurodegenerative disease (1); neuronal ceroid lipofuscinosis 4 A (1); optic atrophy (1); Stargardt disease (1).